IL6 (interleukin 6)
Diseases named in the same sentence as IL6 in open-access papers (continued):
Sharing a sentence is not in itself a finding about the gene and the disease.
ovarian carcinoma (continued). "Additionally, androgen-induced epithelial ovarian cancer proliferation may be partially due to the enhanced IL-6 and IL-8 expression, which could also promote epithelial ovarian cancer growth via activation of the AR gene promoter." (PMID 27741511, 2017). "The ovarian cancer ascites used in our study from patients in advanced disease stages showed a mixture and levels of soluble factors similar to previous studies, with a predominance toward Th2 vs Th1 type cytokines, and high levels of IL-6 and TNF compared to serum." (PMID 29163543, 2017). "In addition, high IL-6 levels in ascites can be used to distinguish patients with advanced serous ovarian cancer from patients with benign conditions and to predict chemoresistance and progression-free survival in ovarian cancer patients." (PMID 26751490, 2016). "Nieman and colleagues showed that, in addition to the promotion of tumor metastasis by adipocyte-derived IL-6 and IL-8, adipocytes directly transferred fatty acids to cancer cells in a co-culture model that consisted of fluorescently labeled lipid-loaded adipocytes and ovarian cancer cells." (PMID 26751490, 2016). "Thus, IL-6/IL-6R mediated JAK2-STAT3 signaling pathway could be a promising therapeutic target for anticancer therapy in ovarian cancer patients with ascites." (PMID 27825119, 2016). "Supporting our findings, clinical studies have shown that elevated IL-6 serum levels correlate with worse patient outcomes, and targeting IL-6 signaling with a neutralizing antibody has shown promising results in a clinical trial for the treatment of ovarian cancer." (PMID 27602757, 2016). "It remains to be determined whether TNFα and IL6 increase STS activity in ovarian cancer cells." (PMID 25817828, 2015). "In addition to above, malignant ascites contains significant numbers of activated CD163+ M2 type of macrophages the presence of which correlates with enhanced levels of IL-6 and IL-10 and inversely correlates with relapse-free survival period in ovarian cancer patients." (PMID 24093089, 2013). "In addition, DIM treatment reduced the levels of IL-6 in ovarian cancer cells and in the tumors." (PMID 22280969, 2012). "Interestingly, a recent study reported higher IL-6 levels in ovarian cancer patients." (PMID 22280969, 2012). "However, it still remains to be determined if activation by EGF or somatic-activating mutations in the kinase domain of EGFR has any effect on the production of IL-6 or GP130 family of cytokines that can lead to the activated status of STAT3 in ovarian carcinomas." (PMID 19088723, 2009). "As a vital immunoregulatory cytokine, IL‐6 mediates chemoresistance through various signaling pathways, with the JAK2/STAT3 signaling pathway being particularly prominent in ovarian cancer." (PMID 40968783, 2026). "As demonstrated in in vitro ovarian cancer cell models, TLR4/IL‐6 provokes AR expression via the PI3K/AKT signaling pathway, among which phosphorylated AKT is essential for the expression of AR." (PMID 40968783, 2026). "OC’s ERα antagonism extends to ER+ endometrial and ovarian cancers, where it suppresses E2-induced IL-6/STAT3 cascades (70% IL-6 reduction at 25 μM) and downregulates progesterone receptor (PR) expression via GREB1 suppression." (PMID 40564985, 2025). "IL-6 additionally induces nuclear translocation and transcriptional activation of HIF-1α via STAT3, enhancing cisplatin resistance in ovarian cancer cells." (PMID 41383608, 2025). "Such evidence is also supported by research on extracellular vesicles in OC, which has shown an overproduction of IL-6 and TGF β1 in the early stages of ovarian carcinoma." (PMID 40428734, 2025). "Following the bioinformatics analysis, the study explored the expression levels of CCL2, IL10, IL6, and TGFβ1 in normal ovarian epithelial cells (HOSE) and ovarian cancer cells (SKOV3)." (PMID 39981173, 2025).
ovarian carcinoma (continued). "Ovarian cancer-TA-MSCs-derived CCL2 and CCL5 increase IL-6 expression in cancer cells, promoting chemotherapy resistance via PYK2 phosphorylation." (PMID 40676710, 2025). "Our study also shows a significant increase in IL-6 levels with olaparib treatment in both BRCA-mutant and BRCA-proficient TNBCs, consistent with findings in ovarian cancer." (PMID 40723906, 2025). "This study aimed to investigate the impact of chronic stress on HDC expression in ovarian cancer progression and the effect of HIS on the IL-6/STAT3/S100A9 pathway." (PMID 39720595, 2024). "Therefore, IL-6 may promote the development of high-grade ovarian cancer." (PMID 38541242, 2024). "Recent studies have shown that the IL-6/STAT3 signalling promotes CSC self-renewal and maintenance in ovarian cancer cells and supports tumor growth in the omental microenvironment." (PMID 38575576, 2024). "Targeted therapy against IL-6 has shown promising results in mouse models and in vitro cell lines of various cancers, by dampening the IL-6/JAK/STAT3 signaling pathway in gastric cancer, ovarian cancer, and pancreatic cancer." (PMID 38689325, 2024). "In ovarian cancer, lncRNA HOTTIP upregulates the expression of PD-L1 in neutrophils via IL-6 secretion, inhibiting T-cell immunity and contributing to immune evasion by cancer cells." (PMID 38226979, 2024). "The visceral ADSCs promote intraperitoneal dissemination by the increasing expression of the chemokines IL-6, MIP-2, and MCP-1 in ovarian cancer." (PMID 38643448, 2024). "TAMs also affect iron storage and release, secrete cytokines such as IL-6, tumor necrosis factor-α (TNF-α), and interferon-γ (IFN-γ) that regulate iron metabolism, and enhance the invasiveness of ovarian cancer cells." (PMID 39061859, 2024). "TFB2M overexpression is also associated with increased extracellular mtDNA and elevated IL-6 expression in ovarian cancer cells and promote the infiltration of M2 macrophages through the cytoplasmic mtDNA/TLR9/NF-κB/IL-6 pathway." (PMID 38589371, 2024). "The findings suggest that while IL6 inhibition alone may have limited standalone clinical efficacy, combining it with other therapeutic agents, particularly chemotherapies or pathway inhibitors, holds significant promise for improving outcomes in ovarian cancer patient." (PMID 39766086, 2024). "This elevation in hormone levels can stimulate the production of MMP-9 by TAMs, creating a favorable environment for angiogenesis, invasion, and the production of VEGF, IL-6, and MMP-9 in patients with ovarian cancer and lung adenocarcinoma." (PMID 38254696, 2024). "Human NK cells exhibit low expression or absence of the IL-6 receptor alpha chain; however, the regulation of ovarian carcinoma SKOV-3 cell proliferation and secretion by autocrine IL-6 has been described." (PMID 39457710, 2024). "The co-cultured ovarian cancer cells show increased expression of PD-L1, VEGF, STAT3, IL-10, IL-6, B-cell lymphoma 2 (BCL2), and MDR1." (PMID 36757936, 2023). "In our study, median values of Il-6 and CRP were, respectively, 16.76 pg/mL (range: 0.5–79.75) and 75.02 mg/L (range: 1–243) for patients with ovarian cancer and 5.92 pg/mL (range: 0.5–40.19) vs. 26 mg/L (range: 1–330) for women with a benign pelvic tumor." (PMID 37373969, 2023). "In conclusion, our study found that the increased IL‐6 and TNF‐α levels in recurrent ovarian cancer patients, while the decreased IFN‐γ level, the CD4+ T‐cell proportion, and the CD4+/CD8+ ratio." (PMID 37904699, 2023). "This study aims to investigate IL6, CA-125 and HE4 to predict tumor resectability in the pre-operative patients with advanced epithelial ovarian cancer." (PMID 37792745, 2023). "Significantly reduced expression of NKG2D, high level of MICA as well as IL-6, IL10 and TNF-α indicates immune suppression of ovarian cancer patients.." (PMID 37322531, 2023).
ovarian carcinoma (continued). "Measuring IL6, CA-125, and HE4 levels is useful for clinicians to predict tumor resectability in pre-operative patients with advanced epithelial ovarian cancer." (PMID 37792745, 2023). "It has shown anti-IL-6 activity, which induces inactivation of STAT3 through IL-6 binding and nuclear accumulation of FoxO3a in ovarian cancer cells." (PMID 37047012, 2023). "After adjusting for confounding factors, the results showed that the serum IL‐6, IFN‐γ, and TNF‐α levels were influencing factors of recurrence in epithelial ovarian cancer patients." (PMID 37904699, 2023). "We demonstrated that IL-6, MDR-1, and BCL2 increased expression in the ovarian cancer cells co-cultured with macrophages." (PMID 36757936, 2023). "Cytokines (IL-6, TNF-α, IL-10, TGF-β) and chemokines (CCL2, CCL4, CXCL10) involved in the ovarian cancer microenvironment have also been shown to contribute to the development of carcinogenesis." (PMID 36765633, 2023). "We determined that TAMs had increased expression of IL-10, IL-6, CD206, and ARG1, whereas ovarian cancer cells had increased expression of IL-10, IL-6, VEGF, STAT3, and PD-L1." (PMID 36757936, 2023). "Olaparib maintenance treatment can significantly decrease the IL‐6 and TNF‐α level, and increase IFN‐γ level and the CD4+/CD8+ ratio in patients with recurrent ovarian cancer." (PMID 37904699, 2023). "Number of platelets, MCH as median concentration, Il-6 and MCHC are less important in detection of ovarian cancer, which was statistically significant in Spearman correlation." (PMID 37373969, 2023). "Statistically significant correlations were found between diagnosis of ovarian cancer and levels of CA125, HE4, CRP, PCT and Il-6." (PMID 37373969, 2023). "Previous studies have also reported high sensitivity and specificity of using a single tumor marker IL6, CA-125, HE4, or combinations to predict ovarian cancer surgical outcomes." (PMID 37792745, 2023). "The role of interleukin‐6 (IL‐6), tumor necrosis factor‐α (TNF‐α), and IFN‐γ in the development of ovarian cancer has attracted much attention." (PMID 37904699, 2023). "In comparison between early (I and II according to FIGO classification) and late (III and IV according to FIGO classification) stages of ovarian cancer, statistically significant impacts were detected for the algorithm Ca125, HE4, CRP and Il-6." (PMID 37373969, 2023). "Combined anti-CD47 therapy with olaparib also reduced cytokine secretion of IL6, IL18 and CCL2 from ovarian cancer cells." (PMID 37468567, 2023). "This study highlights the importance of evaluating tumor marker (IL6, CA-125, and HE4) levels to predict tumor resectability in pre-operative patients with advanced epithelial ovarian cancer." (PMID 37792745, 2023). "Recently, we have confirmed the formation of IL-6/STAT3/HIF-1α autocrine signaling loop in ovarian cancer cells in vitro and in vivo, which confers chemoresistance against cisplatin to ovarian cancer." (PMID 36814597, 2023). "We previously reported that in ovarian cancer cells grown as 2D, the level of ARH-I is reduced by IL-6 and increased by RV, respectively." (PMID 35565270, 2022). "In general, higher serum levels of Il-10, Il-6, and TGF-β are reported in women with advanced ovarian cancer compared to controls." (PMID 35565348, 2022). "In conclusion, due to crosstalk between IL6/LIF cytokine signaling and estrogen signaling, dual blockade is a potential new treatment approach for ovarian cancer." (PMID 36230597, 2022). "Platinum-agents have demonstrated increased IL-6 and PGE2 production in ovarian cancer cell lines, with subsequent activation of STAT3 pathway and induction of M2 polarization with upregulation of IL-10." (PMID 35565348, 2022). "IL-6 activates the JAK-STAT3 pathway, and thereby promotes the invasion and metastasis of ovarian cancer cells." (PMID 34751020, 2022).
ovarian carcinoma (continued). "Adipocytes secrete a vast array of cytokines including IL-6, IL-8, monocyte chemoattractant protein-1 (MCP-1), and adiponectin, which home ovarian cancer cells to the omentum and encourage their adhesion and invasion to the organ." (PMID 35574025, 2022). "We will then evaluate and determine the mechanisms involved in ovarian cancer tumor growth by measuring levels of anandamide and 2-arachidonoyl glycerol as well as protein levels of CB1, CB2, ERα, ERβ, GPER, TNFα, IL-1β and IL-6 in ovarian and tumor tissues." (PMID 35242036, 2022). "Exploration of this phenotypic shift found that cross-linking of MOv18 IgE on human monocytes by ovarian cancer cells, induced a pro-inflammatory secretome (TNF-α, CCL2, IL-10, CXCL-10, IL-1β, IL-6, and IL-23)." (PMID 35020853, 2022). "Compartmental CRS (C-CRS) was reported in a patient with advanced ovarian cancer treated with mesothelin-targeted CAR T cells, characterised by the elevation of IL-6 and accumulation in the pleural fluid." (PMID 35565412, 2022). "For instance, conditioned media derived from CD45−/CD31− adipose stromal cells, which are isolated from subcutaneous or visceral fat, was shown to activate the JAK2/STAT3 pathway via IL-6 and enhance migration in SKOV3 ovarian cancer cells." (PMID 35565396, 2022). "The cutoff values for the interleukin 6, interleukin 8, and TNF-α that were elevated in patients with ovarian carcinoma (OC Group) were calculated using ROC curve analysis." (PMID 34573967, 2021). "At this regard, in 1998 we had demonstrated that high levels of pro-inflammatory cytokines such as IL-6, tumor necrosis factor (TNF)-α, IL-1, and CRP are correlated with impaired T-cell responses in women with advanced epithelial ovarian cancer." (PMID 33550983, 2021). "Epidermal growth factor receptor (EGFR) signalling and the interleukin-6 (IL-6)/signal transducer and activator of transcription 3 (STAT3) are aberrantly activated in ovarian cancer." (PMID 34369236, 2021). "Moreover, in ovarian cancer, treatment with cisplatin or carboplatin increased IL-6 secretion by cancer-associated fibroblasts, which promoted enrichment of ADLH+ CSC, consistent with IL-6 mediated EMT activation in gastric cancer and a tight correlation between CSC plasticity and EMT." (PMID 33451077, 2021). "Similarly, in 2018, Thorsson, while determining the immune phenotype associated to several types of cancer, showed that ovarian cancer had the highest M1/M2 ratio, among other cancers, associated with a prevalence of CD8+ cells and cytokines made by activated Th1 and Th17 cells, including IL-6." (PMID 33550983, 2021). "We further found that miR-146b blocked the secretion of IL-6 and markedly inhibited phosphorylation of STAT3 at Tyr705 and Ser727 in ovarian cancer cells." (PMID 34369236, 2021). "Oncoprint profile of CYCS, VEGFA, IL6, UQCRC1, UQCRFS1, COX5B, ACKR3/CXCR7, and FYN indicated that these genes were either amplified or overexpressed in 4–25% of the ovarian cancer patients." (PMID 34439877, 2021). "Together, the present study has established the role of nanocurcumin as adjunctive treatment to cisplatin in the ovarian cancer model through inhibition of TGF-β/PI3K/Akt and IL-6/JAK/STAT3 pathways." (PMID 33536913, 2020). "Numerous growth factors and cytokines, including those assessed in our study, such as IL-6, IL-8, MCP-1, RANTES, GRO-alpha, and VEGF, are involved in promoting tumor growth and ovarian cancer cell aggressiveness." (PMID 33266317, 2020). "IL-6 leads to activation of the STAT3 pathway, which is required for ovarian cancer cell migration, motility, survival and proliferation." (PMID 32456078, 2020). "We detected IL-6R expression in clinical ovarian cancer patient’s sample by IHC and found that IL-6R expression was much higher in ovarian cancer tissues (p < 0.05), which might indicate that high levels of IL-6R would be required for PD-L1 induced via the miR-21/IL-6 feedback loop." (PMID 32927431, 2020).
ovarian carcinoma (continued). "The potential use of peripheral blood IL-6 concentration as a screening tool is promising with IL-6 levels found significantly elevated in early stages (FIGO Stage I and II) of ovarian cancers compared to benign ovarian masses or healthy controls." (PMID 32042020, 2020). "The present results confirm that high levels of IL-6 are present in the peritoneal cavity of patients with severe OHSS and in patients with advanced ovarian cancer." (PMID 32138790, 2020). "We also prove for the first time that p-STAT3/NF-kB is loop to increase the expression of IL-6 and VEGF, and IL-6 and VEGF create a feedback to p-STAT3/NF-kB loop in ovarian cancer cells." (PMID 32190078, 2020). "Intestinal dysbiosis stimulates the growth of xenograft tumors and induces the development of epithelial-mesenchymal transition in ovarian cancer cells, which activates TAM via the secretion of IL-6 and TNF-α." (PMID 32133297, 2020). "The pro-inflammatory cytokines IL-6, IL-8 and TNF-α are commonly present in the ascites of ovarian cancer patients." (PMID 32727400, 2020). "In ovarian cancer, IL-6 induces STAT3 expression that in turn activates hypoxia inducible factor (HIF), resulting in the resistance of patients with ovarian cancer to chemotherapy with sunitinib." (PMID 32545648, 2020). "At-EE did not influence vascular endothelial cells directly, but decreased IL-6 and VEGF secreted by ovarian cancer cells to inhibit angiogenesis through inhibition of p-STAT3 and NF-kB activation." (PMID 32190078, 2020). "Several adverse clinical markers are highly expressed by ovarian cancer TAMs, including CD163, Procollagen C-endopeptidase enhancer 2 (PCOLCE2), IL-6 and IL-10." (PMID 32774171, 2020). "The expression of pro-inflammatory factors, such as IL-1, IL-6, TNF-α and COX-2, dues to the histological heterogeneity of ovarian cancers." (PMID 31088412, 2019). "LPA is identified to elevate IL-6, IL-8 and VEGF through Akt/ nuclear factor kappa B (NF-kB) pathway in ovarian cancer cells." (PMID 31202269, 2019). "Ovarian cancer G protein-coupled receptor 1 (OGR1) senses extracellular protons and mediates the production of interleukin-6 (IL-6) and connective tissue growth factor (CTGF) in ASMCs." (PMID 30828266, 2019). "It is very plausible that this effect was associated with the higher secretion levels of several agents known to support ovarian cancer cell progression by these cells, such as CCL2, CXCL8, CXCL12, ICAM-1, IL-6, HGF, PAI-1, uPA, TGF-β1, and VEGF." (PMID 31086083, 2019). "IL-6, LIF, and IL-11 secreted in the EOC tumor microenvironment function in concert to induce ovarian cancer cell JAK-STAT signaling." (PMID 31861720, 2019). "As the metastatic tumor grows and depletes the adipocytes in the omentum, the IL-6, CXCL10, and CCL5 secreted by the CAFs induce the ovarian cancer cells to start utilizing glycogen." (PMID 30380628, 2018). "In ovarian cancer, the evidence of induction of cancer stem cells is limited, with a few reports indicating the role of CAF derived fibroblast growth factor 4 and IL-6 in inducing cancer stem cells." (PMID 30380628, 2018). "In an epithelial ovarian-cancer (EOC) xenograft model, human bone-marrow mesenchymal stem cells were shown to give rise to CAFs that produced IL-6 to enhance tumor growth." (PMID 30200478, 2018). "In the case of ovarian cancer cells, their motility was fueled by CXCL1/GRO-1, CXCL8/IL-8, IL-6, TGF-β1, and fibronectin." (PMID 28956065, 2018). "Several other groups have also shown many chemokines and cytokines, including IL-6, COX-2, and CXCL1, to be involved in tumor-related inflammation in epithelial ovarian cancer." (PMID 30380628, 2018). "Ovarian cancer cell expression HOXA9 induces CAFs to secrete CXCL12, IL-6, and VEGF-A expression, which promotes angiogenesis." (PMID 30380628, 2018).